AFF2 (ALF transcription elongation factor 2)
Diseases named in the same sentence as AFF2 in open-access papers (continued):
Sharing a sentence is not in itself a finding about the gene and the disease.
Bardet-Biedl syndrome (1 paper, 2021). A ciliopathy with multisystem involvement. "For example, HES2, MAFB, RPS12, RPL12, RPS15, and AFF2 are all associated with cancer, whereas BBS12 is a gene related to Bardet-Biedl Syndrome, a multi-organ genetic disease that can involve hypoplasia of the uterus, ovaries, and fallopian tubes." (PMID 34215221, 2021).
breast tumors (1 paper, 2015). "It has been demonstrated that AFF2 mutations are associated with breast tumors." (PMID 25351872, 2015).
frontotemporal dementia (1 paper, 2023). Frontotemporal dementia (FTD) comprises a group of neurodegenerative disorders, characterized by progressive changes in behavior, executive dysfunction and language impairment, as a result of degeneration of the medial prefrontal and frontoinsular cortices. "In ALS and frontotemporal dementia (FTD), AFF2/FMR2 regulates the expression of the C9orf72 allele containing G-rich sequences, and knockdown of AFF2/FMR2 decreases the expression of the mutant allele, resulting in the rescue of axonal degeneration and TDP-43 pathology." (PMID 37323535, 2023).
hemophilia B (1 paper, 2018). Hemophilia B is a form of hemophilia characterized by spontaneous or prolonged hemorrhages due to factor IX deficiency. "Our patient was diagnosed with mild hemophilia B after finding an 11 Mb deletion of Xq26.3q28 that included the following genes among others IDS,SOX3,FMR1,AFF2, and F9." (PMID 30264515, 2018).
HIV-1 infection (1 paper, 2024). The type species of lentivirus and the etiologic agent of acquired immunodeficiency syndrome (AIDS). "It does provide, however, further evidence that AFF2 plays an essential role during HIV-1 infection." (PMID 39122863, 2024).
microcephaly (1 paper, 2022). A congenital or acquired developmental disorder in which the circumference of the head is smaller than normal for the person's age and sex. "The syndromes or intellectual developmental disorders caused by variants in DIAPH1, AFF2, BCORL1 and BRWD3 are occasionally with abnormalities of cranium, such as microcephaly or macrocephaly tall forehead." (PMID 36118902, 2022).
neuroblastoma (1 paper, 2020). Neuroblastoma (NB) is the most common solid, extracranial childhood tumor. "We found several highly significant RBPs including RPL22L1, RNASEH2A, PTRH2, MRPL11 and AFF2, which remain uncharacterised in neuroblastoma." (PMID 32707690, 2020).
papilloma (1 paper, 2025). A benign epithelial neoplasm that projects above the surrounding epithelial surface and consists of villous or arborescent outgrowths of fibrovascular stroma. "Histopathological evaluation revealed that DEK::AFF2 carcinomas frequently exhibit a complex architecture, including endophytic and exophytic, often papilloma-like growth patterns." (PMID 40688086, 2025).
Parkinson disease (1 paper, 2021). A progressive degenerative disorder of the central nervous system characterized by loss of dopamine producing neurons in the substantia nigra and the presence of Lewy bodies in the substantia nigra and locus coeruleus. "Association between AFF2 and Parkinson’s disease clinical features such as gait disorder, visual hallucination and urinary incontinence have been observed, however studies with larger cohorts are needed to further understand the AFF2 role in the disease progression and manifestation." (PMID 34282157, 2021).
ventricular septal defect (1 paper, 2023). The presence of a defect (opening) in the septum that separates the two ventricles of the heart. "A duplication of Xq28 including the AFF2 gene was detected in a male fetus referred for prenatal chromosomal microarray analysis due to ultrasonographic findings of a ventricular septal defect and persistent left superior vena cava." (PMID 37628571, 2023).
carcinoma (14 papers, 2011 to 2025). A malignant tumor arising from epithelial cells. "DEK::AFF2 fusion-associated carcinomas of the sinonasal tract are exceedingly rare, with fewer than 100 cases reported worldwide, but probably underrecognized." (PMID 40688086, 2025). "DEK::AFF2 fusion-associated carcinomas are often initially misdiagnosed as inverted sinonasal papillomas due to their deceptively benign histological appearance." (PMID 40688086, 2025). "We report two cases of DEK::AFF2 fusion-associated carcinomas managed at Saarland University Medical Center." (PMID 40688086, 2025). "The particular molecular signature of DEK::AFF2 sinonasal fusion-associated carcinomas come along with unique clinical challenges, especially due to the absence of standardized therapeutic protocols." (PMID 40688086, 2025). "These cases highlight the aggressive nature of DEK::AFF2 fusion-associated carcinomas and the critical role of genetic profiling in diagnosis and management." (PMID 40688086, 2025). "DEK::AFF2 fusion-associated carcinomas have been described recently as an emerging entity in the sinonasal tract, with the majority showing a strikingly bland histologic appearance and overlap with so-called low-grade papillary Schneiderian carcinomas." (PMID 37118352, 2023). "In order to address the differential diagnosis of a DEK::AFF2 fusion-associated carcinoma, molecular profiling was performed using the FoundationOne® Heme test." (PMID 37118352, 2023). "To conclude, the DEK::AFF2 fusion-associated carcinoma was recently detected as a distinct variant of SNSCC." (PMID 36431263, 2022). "In a patient with DEK::AFF2 fusion-associated carcinoma, an exceptional response to ICIs was identified." (PMID 36431263, 2022). "A recently described molecularly distinct variant of SNSCC is the DEK::AFF2 fusion-associated carcinoma." (PMID 35326613, 2022). "Implementing such a diagnostic algorithm may facilitate earlier detection of DEK::AFF2 fusion-associated carcinomas and inform timely, individualized therapeutic strategies." (PMID 40688086, 2025). "Our previous study demonstrated that AFF2 IHC reliably identifies DEK::AFF2 carcinoma, with tumor cells exhibiting moderate to strong nuclear staining in at least 30% of cells." (PMID 40299135, 2025). "Accurate recognition of DEK::AFF2 carcinoma is essential to prevent misdiagnosis and ensure appropriate clinical management." (PMID 40299135, 2025). "Tumors harboring H3-3A::AFF2 and NUCKS1::AFF2 fusions exhibited bland transitional cell-like morphology with acantholytic changes similar to classic DEK::AFF2 carcinoma; the NUCKS1 fusion also demonstrated clear cell features." (PMID 40494991, 2025). "who reported a case of DEK::AFF2 fusion carcinoma with lung metastases demonstrating an exceptional response to PD-1 inhibition therapy (pembrolizumab), despite negative PD-L1 expression." (PMID 40688086, 2025). "DEK::AFF2 carcinomas consistently express squamous cell markers, such as p40, CK5/6 and p63, while typically negative for synaptophysin, NUT, and p16." (PMID 40299135, 2025). "Given the consistent involvement of the AFF2 gene and uniform AFF2 immunohistochemical positivity despite morphological heterogeneity, we propose naming this entity AFF2 carcinoma." (PMID 40494991, 2025). "This case underscores the potential for DEK::AFF2 carcinoma to occur throughout the entire respiratory tract, including the larynx." (PMID 40299135, 2025). "As our understanding of these tumors evolves, new entities, such as DEK::AFF2 carcinoma, are being identified, further expanding the spectrum of sinonasal malignancies." (PMID 39766144, 2024). "The other morphologic mimics of MEC, including SCC, and DEK::AFF2 fusion-associated papillary SCC, were renamed “DEK::AFF2 carcinomas”." (PMID 38429827, 2024).
carcinoma (continued). "The original case report on the entity describes a DEK::AFF2 carcinoma with an excellent response to immune checkpoint inhibitors (ICI)—anti-PD-L1—which is related to DEK::AFF2 neoantigen-specific T-cell response during tumor regression." (PMID 38491228, 2024). "The new entity of DEK::AFF2 carcinomas was diffusely positive for CK5/6, p40, and p63, and negative for CK7." (PMID 38429827, 2024). "DEK::AFF2 carcinomas have been successfully immunostained for AFF2 protein, and all cases showed positive nuclear expression." (PMID 38491228, 2024). "Overall, the distinctive molecular and histologic features of DEK::AFF2 carcinomas suggest that they represent a unique entity in the sinonasal region." (PMID 38429827, 2024). "A carcinoma with DEK::AFF2 gene fusion was considered as the primary differential diagnosis on morphologic grounds." (PMID 37118352, 2023). "The immunoprofile of DEK::AFF2 carcinomas is in accordance with a squamous phenotype, being diffusely p63 and p40 positive." (PMID 35326613, 2022). "Second, the proposed approach also enables identification and exploration of driver genes; our analyses implicate DMD, RSK4, OFD1, WDR44, and AFF2 as potential cancer drivers." (PMID 35753349, 2022). "Postmortem analysis of FFPE tissue samples obtained during surgery in April 2019 was reinterpreted as being consistent with DEK::AFF2 carcinoma which was then confirmed by detection of the DEK-AFF2 fusion, underscoring its role in the aggressive disease progression." (PMID 40688086, 2025). "Given the novelty of DEK::AFF2 fusion-associated carcinomas, standardized treatment protocols are currently lacking." (PMID 40688086, 2025). "All DEK::AFF2 carcinomas are diffusely positive for p63 and p40." (PMID 38491228, 2024). "As an alternative, AFF2 IHC has been validated as a sensitive and specific ancillary marker for DEK::AFF2 carcinoma, serving as a surrogate for molecular confirmation." (PMID 40299135, 2025). "Here, we report the first documented case of primary laryngeal SCC with DEK::AFF2 fusion, suggesting that this carcinoma may not be restricted to the sinonasal tract and skull base but could potentially arise throughout the respiratory tract epithelium." (PMID 40299135, 2025). "Accordingly, AFF2 immunohistochemistry represents an emerging highly sensitive and specific ancillary marker that distinguishes DEK::AFF2 carcinoma from other sinonasal tumors with overlapping morphological features, and it may also be useful in decalcified specimens." (PMID 38491228, 2024). "To date, DEK::AFF2 carcinoma has been considered a malignancy confined to the upper respiratory tract, with only one primary lung SCC with DEK::AFF2 fusion reported in a 26-year-old female never-smoker." (PMID 40299135, 2025).
tumor (8 papers, 2011 to 2025). "In contrast, the EWSR1::AFF2 fusion tumor showed high-grade adenocarcinoma morphology with focal neuroendocrine marker expression, lacking p63 and CK5/6." (PMID 40494991, 2025). "MYCBP2, AFF2, and C3 influenced patient outcomes by affecting tumor growth, metastasis, and treatment resistance." (PMID 40729021, 2025).
neurodevelopmental disorder (5 papers, 2019 to 2024). A behavioral and cognitive disorder with onset during the developmental period that involves impaired or aberrant development of intellectual, motor, or social functions. "TFs associated with neurodevelopmental disorders, such as Npas1 and Npas3, are preferentially expressed in DR-6, and Aff2 is enriched within DR-3." (PMID 31647409, 2019). "Intragenic deletions of AFF2 have been identified in patients with ID and an excess of point mutations in AFF2 has been described in males with ASD, further supporting the association of this gene with neurodevelopmental disorders." (PMID 38835438, 2021).
neurological disease (2 papers, 2011 to 2017). "We identified four genes that had already been associated with neurological disorders (AFF2, ALG13, OPHN1, and RBM10)." (PMID 28769055, 2017).
gastrointestinal disorders (1 paper, 2018). "And in patient ASD-667 with a missense mutation in AFF2 displayed gastrointestinal disorders in addition to DD/ID." (PMID 30555518, 2018).
AFF2 also shares sentences with these, for which no sentence is quoted: genetic disease (4 papers); head and neck squamous cell carcinoma (4); Hunter syndrome (3); Obesity (3); scrub typhus (3); Cognitive impairment (2); murine typhus (2); Purpura Fulminans (2); Rett syndrome (2); Rickettsia infection (2); adenocarcinoma (1); and basaloid carcinomas (1); anterior uveitis (1); attention deficit-hyperactivity disorder (1); bladder cancer (1); bladder urothelial carcinoma (1); CNS tumor (1); Cornelia de Lange syndrome (1); Creatine deficiency syndrome (1); developmental delay (1); Epileptic seizures (1); eye problems (1); glaucoma (1); head and neck tumors (1); hepatocellular carcinoma (1); infection (1); leukemia (1); lung carcinoma (1); melanoma (1); memory impairment (1).
A further 11 diseases each share a sentence with AFF2 in 1 paper.